ST18 (ST18 C2H2C-type zinc finger transcription factor)
Description:
Repressor that binds to DNA sequences containing a bipartite element consisting of a direct repeat of the sequence 5'-AAAGTTT-3' separated by 2-9 nucleotides. Represses basal transcription activity from target promoters (By similarity). Inhibits colony formation in cultured breast cancer cells.
Synonyms: KIAA0535; ZNF387; ZC2HC10; NZF3; NZF-3; ZC2H2C3
Tractability: No criterion of Open Targets' tractability assessment is met for any kind of drug.
Gene: Protein-coding gene on chromosome 8 (52,110,838 to 52,460,983, reverse strand). Ensembl gene ENSG00000147488.
Subcellular location: Nucleus
Gene Ontology:
Molecular function: RNA polymerase II cis-regulatory region sequence-specific DNA binding; DNA-binding transcription factor activity, RNA polymerase II-specific; zinc ion binding
Biological process: interleukin-1-mediated signaling pathway; interleukin-6-mediated signaling pathway; negative regulation of cell population proliferation; positive regulation of transcription by RNA polymerase II; tumor necrosis factor-mediated signaling pathway; regulation of gene expression; regulation of DNA-templated transcription
Cellular component: nucleus; protein-DNA complex; chromatin
Genetic constraint (gnomAD): Loss-of-function variants: 45 observed, 103.88 expected, observed/expected ratio (o/e) 0.43, 90% interval 0.34 to 0.56. The upper end of that interval is the gene's LOEUF score, 0.56, which puts it in group 2 of 6, group 1 being the genes least tolerant of losing a copy. Missense variants: 1,258 observed, 1,288.4 expected, observed/expected ratio (o/e) 0.98, 90% interval 0.93 to 1.02. Synonymous variants: 447 observed, 457.77 expected, observed/expected ratio (o/e) 0.98, 90% interval 0.9 to 1.06.
Homologues: Orthologues: chimpanzee ST18 (99% identical), macaque ST18 (98% identical), rabbit ST18 (89% identical), dog ST18 (86% identical), pig ST18 (86% identical), rat St18 (86% identical), guinea pig ST18 (85% identical), mouse St18 (85% identical), tropical clawed frog st18 (64% identical), Caenorhabditis elegans ztf-11 (13% identical), Drosophila melanogaster Pits (6% identical), Caenorhabditis elegans ifbp-1 (5% identical). Paralogues in human: MYT1 (46% identical), MYT1L (46% identical), IRF2BPL (10% identical), IRF2BP2 (9% identical), IRF2BP1 (9% identical).
Diseases named in the same sentence as ST18 in open-access papers:
ST18 is named in the same sentence as 36 diseases in open-access papers, as found by Europe PMC text mining. Sharing a sentence is not in itself a finding about the gene and the disease. The quoted sentences say what the papers report.
breast carcinoma (9 papers, 2005 to 2022). "ST18, another zinc finger transcription factor-encoding gene related to primary angle-closure glaucoma and breast cancer, was found to be highly expressed in the BCs." (PMID 35386199, 2022). "Hypermethylation of the promoter region of ST18 (breast cancer suppressor gene 18) and expression loss of ST18 in tumor cells of breast cancer patients suggest that this epigenetic mechanism is a marker responsible for tumor-specific down-regulation." (PMID 35174173, 2021). "Furthermore, ST18 plays a variety of other roles, such as inhibiting breast cancer cells, regulating TNFα, inducing pancreatic β-cell apoptosis, and impairing insulin secretion; however, many of its biological functions have not yet been determined." (PMID 35783123, 2022). "However, one of the first reports validated ST18 as a suppressor of tumor growth in breast cancer cell lines." (PMID 31057535, 2019). "These included LAMA3 mutations (lung squamous) and NOS1 mutations (breast cancer), which were identified as MEK inhibitor-specific biomarkers, and ST18 mutations (lung adenocarcinoma and ovarian cancer), which were identified as HDAC inhibitor-specific biomarkers." (PMID 28561042, 2017). "ST18 was found lost, hypermethylated and its mRNA downregulated in breast cancer." (PMID 21151896, 2010). "ST18 (Myt3) is a candidate tumor suppressor in breast cancer; ectopic expression in MCF-7 breast cancer cells strongly inhibits colony formation in soft agar and the formation of tumors in a xenograft mouse model; it is also known to function as an pro-apoptotic effector." (PMID 25023465, 2014).
liver cancer (4 papers, 2013 to 2023). An epithelial or non-epithelial malignant neoplasm that arises from the liver. "For example, in some cases a known proto-oncogene or TSG might not have been linked to a specific tumor type (e.g., the role of ST18 in liver cancer development was determined a few years after the L1 insertion in this gene was reported)." (PMID 28561751, 2017). "L1 insertion in the suppression of tumorigenicity 18 (ST18) gene, a transcriptional repressor, activates ST18 expression in several liver cancer cells." (PMID 38136578, 2023). "This group concluded that ST18 is likely a proto-oncogene that has a role in driving liver cancer in this case." (PMID 28561751, 2017). "Although ST18 is poorly expressed in liver, we found it to be abundant in several liver cancer cell lines." (PMID 23540693, 2013). "Because the expression of ST18 is upregulated in several liver cancer cells and in tumors in a mouse-model for inflammation-driven HCC, and L1 insertion upregulates the expression of ST18, L1 can enhance tumorigenesis through the upregulation of ST18 by an L1 de novo insertion to the ST18 locus." (PMID 30717368, 2019).
pemphigus vulgaris (4 papers, 2016 to 2026). Pemphigus is a group of chronic autoimmune skin diseases characterized by blister formations on the outer layer of the skin and the mucous membranes. "Recently, a genetic variant of the Suppression of tumorigenicity 18 (ST18) promoter was reported to cause ST18 up-regulation, associated with pemphigus vulgaris (PV)-IgG-mediated increase in cytokine secretion and more prominent loss of keratinocyte cohesion." (PMID 31057535, 2019). "Our findings therefore support a direct role for ST18 in the pathogenesis of pemphigus vulgaris, and position ST18 as a new molecular target of potential interest for the treatment of disease." (PMID 27148741, 2016).
pemphigus (3 papers, 2018 to 2024). Pemphigus is a group of rare autoimmune diseases that cause blistering of the skin and mucous membranes (mouth, nose, throat, eyes, and genitals).This conditioncan occur at any age, but often strikes people in middle or older age. "Genetics are implicated in its etiology, with the ST18 gene identified as a potential risk factor for pemphigus in certain populations, suggesting its role as a novel molecular target for therapeutic intervention." (PMID 38737652, 2024). "The mediator abolished loss of cell cohesion in monolayers transfected with ST18 and incubated with pemphigus antibodies indicating that ST18-mediated loss of adhesion is at least in part induced by ERK signaling pathway modulation." (PMID 31057535, 2019). "Most importantly, ST18 overexpression in pemphigus skin confers a significant risk for the disease by both upregulating apoptosis and disrupting keratinocyte adhesion." (PMID 29535737, 2018). "Additionally, the effect of ST18 overexpression on cytokine release but also on the modulation of pemphigus-associated ERK signaling was evaluated since both events would render keratinocytes more susceptible to PV-IgG-induced loss of keratinocyte adhesion." (PMID 31057535, 2019). "Here we tested the effects of PV-IgG and the pathogenic pemphigus mouse anti-Dsg3 antibody AK23 on cytokine secretion and ERK activity in human keratinocytes dependent on ST18 expression." (PMID 31057535, 2019). "Taken together, our study adds new insight on the mechanisms by which ST18 may contribute to pemphigus pathogenesis and indicates that altered signaling mechanisms regulating desmosomal adhesion may render keratinocytes more susceptible to autoantibody-induced loss of cell adhesion." (PMID 31057535, 2019).
type 2 diabetes (3 papers, 2024 to 2026). "In type 2 diabetes, genes like ST18, SNAP91, and SLBP are more central in the network, showing their importance in dealing with ongoing metabolic stress." (PMID 40909129, 2025).
Alzheimer disease (2 papers, 2023). A progressive, neurodegenerative disease characterized by loss of function and death of nerve cells in several areas of the brain leading to loss of cognitive function such as memory and language. "A GWAS for Alzheimer disease found that ST18 was associated with cortical atrophy." (PMID 38063329, 2023).
lung adenocarcinoma (2 papers, 2010 to 2017). A carcinoma that arises from the lung and is characterized by the presence of malignant glandular epithelial cells. "We performed high-resolution array comparative genomic hybridization analysis of lung adenocarcinoma in sixty never smokers and identified fourteen new minimal common regions (MCR) of gain or loss, of which five contained a single gene (MOCS2, NSUN3, KHDRBS2, SNTG1 and ST18)." (PMID 21151896, 2010).
acute myeloid leukemia (1 paper, 2022). Acute myeloid leukemia (AML) is a group of neoplasms arising from precursor cells committed to the myeloid cell-line differentiation. "Recently, the downregulation of ST18 was associated with short event-free survival in acute myeloid leukemia." (PMID 36010616, 2022).
asthma (1 paper, 2022). "The other two DMPs -cg00456326 in the TSS1500 of OSR1 and cg20259981 in the TSS1500 of ST18- have been associated with atherosclerosis and Down syndrome and with asthma, respectively." (PMID 35836279, 2022). "Down syndrome (11 associations) and asthma (7 associations) are most reported for the ST18 gene." (PMID 35836279, 2022).
breast tumors (1 paper, 2022). "These were a frameshift variant on ALPK1, a gene with downregulated expression in lung and colorectal tumors, and a frameshift variant on ST18, a gene with tumor-suppressing activity in breast tumors." (PMID 36077770, 2022).
dementia (1 paper, 2023). Loss of intellectual abilities interfering with an individual's social and occupational functions. "Importantly, five of these pre-mRNAs (DOCK1, HOMER1, MAN2A1, RTN4, and ST18) were also found to correlate with dementia severity in the parietal cortex, suggesting that these circRNAs in general correlate with AD progression." (PMID 37266374, 2023).
endometrial tumor (1 paper, 2022). "In this patient, with an endometrial tumor diagnosed at age 53 and loss of MLH1/PMS2 expression, we identified two variants classified as pathogenic and likely pathogenic in the ATM and ST18 genes, respectively." (PMID 36077770, 2022).
head and neck cancer (1 paper, 2025). A primary or metastatic malignant neoplasm affecting the head and neck. "Methylation of ST18 in a study of head and neck cancer (HNC) by Ribeiro was also found to have a prognostic effect on patients." (PMID 40869909, 2025).
Insulin resistance (1 paper, 2022). Increased resistance towards insulin, that is, diminished effectiveness of insulin in reducing blood glucose levels. "The genes HOXA5 and ST18 have been implicated in biological processes relevant to insulin resistance." (PMID 35836279, 2022). "In the GWAS catalog, we found out that genetic variants annotated to HOXA5, OSR1 and ST18 were not independently related to insulin resistance traits." (PMID 35836279, 2022).
migraine (1 paper, 2022). "There is limited information regarding ST18, but based on our results and the relationship between ST18 and inflammation and the intensity of ST18 in the brain, we believe that this gene will be a potential marker for migraine and the focus of our future research." (PMID 35783123, 2022).
neuroblastoma (1 paper, 2019). Neuroblastoma (NB) is the most common solid, extracranial childhood tumor. "Overall, we found that downregulation of 7 genes (Crb1, Lrrc9, Rcn1, Rtl1, Shisa3, Six6, St18) and upregulation of 2 genes (C1ql3, Slc18A1), are strongly predictive of favorable neuroblastoma outcome, consistent with delayed tumor development in Th-MYCN/Casp2−/− mice." (PMID 30670683, 2019).
Obesity (1 paper, 2026). Accumulation of substantial excess body fat. "Under obesity-induced stress as xenotransplants, ST18-KD also caused beta cell death." (PMID 42247169, 2026).
parasitemia (1 paper, 2021). "Moreover, ST18 induced the activation, in infected macrophages, of caspase-1, a conserved enzyme that plays a major role in controlling parasitemia, host survival and the onset of the adaptive immune response in Trypanosoma infection." (PMID 34832980, 2021).
tumor (16 papers, 2005 to 2025). "ST18 overexpression was associated with tumor progression and metastasis and contributed to the determination of small residual diseases (MRD)." (PMID 35735600, 2023). "It has since been demonstrated that ST18 is important for the development and persistence of liver tumors by facilitating interactions with tumor associated macrophages." (PMID 28561751, 2017). "The remaining tumor-specific L1 insertion occurred in donor 47 and was associated with activation of the transcriptional repressor suppression of tumorigenicity 18 (ST18), a member of the MYT1 zinc-finger transcription factor family." (PMID 23540693, 2013). "The ST18 gene has been proposed to act either as a tumor suppressor or as an oncogene in different human cancers and correlated with poor outcomes." (PMID 35735600, 2023). "For example, a tumor-specific L1 somatic insertion is found at the transcriptional repressor suppression of tumorigenicity 18 (ST18) gene, a candidate oncogene in the liver, and the insertion activates ST18 expression." (PMID 30717368, 2019). "In the second example, suppression of tumorigenicity 18 (ST18) was activated by a tumor-specific L1 insertion." (PMID 23540693, 2013). "To corroborate this result, we performed an immunoblot and immunohistochemistry with an anti-ST18 antibody and found ST18 was indeed ectopically expressed in donor 47 tumor." (PMID 23540693, 2013). "Finally, in view of the clonal amplification of tumor cells containing ectopically expressed ST18, we engaged complementary in vitro and in vivo experimental models to assess ST18 oncogenic function in HCC." (PMID 23540693, 2013). "Contrasting reports depict ST18 as a tumor suppressor and as an oncogene in different cancers." (PMID 23540693, 2013). "Thus, tumor cells containing the ST18 L1 mutation were clonally amplified without CNV of the ST18 locus, followed by ST18 transcriptional activation." (PMID 23540693, 2013). "Representative protein expression of MEOX2, PHYHIP, RBBP8, ST18, TCF12, and THRB in tumor tissues was demonstrated based on immunohistochemical analysis in the HPA database." (PMID 40869909, 2025). "Several genes previously reported as subgroup-specific drivers or tumor lineage markers, such as PTCH1, PDE1C, and ST18 in SHH and OTX2, EOMS, and LMX1A in G3, were recovered and detected as DEGs exclusively in GNP and RL, respectively." (PMID 41029754, 2025). "In human cancers, some ZFPs, including ZAC, ST18, ZNF382 and ZNF331, function as tumour suppressors and are frequently inactivated by CpG methylation." (PMID 25714013, 2015). "Several ZFPs, such as ZNF217 and ZNF639, are oncogenic proteins, whereas other ZFPs, such as ZAC, ST18, ZNF382 and ZNF331, are tumour suppressors." (PMID 25714013, 2015). "An assessment of the twenty-nine enteroendocrine-related transcription factors identified that ST18, INSM1 and NKX2-2 were commonly expressed in both tumor sets." (PMID 25023465, 2014). "Our profiles indicate that RARβ2 induces a number of tumor suppressor functions (NDRG1, RPL10, and ST18) and known metastasis suppressors (NDRG1 and TYRP1)." (PMID 16255778, 2005). "ST18 is, however, very poorly expressed in liver, making it unlikely to act as a tumor suppressor in this context." (PMID 23540693, 2013). "QRT-PCR indicated that ST18 expression was significantly increased in tumor versus adjacent nontumor liver (p < 0.005, t test, df = 4)." (PMID 23540693, 2013). "Thus, we experimentally validated a model of ST18 activation in which a negative feedback loop was interrupted by a tumor-specific L1 insertion." (PMID 23540693, 2013). "However, we do not make any conclusion regarding the function of ST18 as a tumor suppressor or oncogene outside of the liver and draw attention in this matter to KLF4, a transcriptional repressor known to function as a tumor suppressor and as an oncogene, depending on context." (PMID 23540693, 2013).
tumor (continued). "MEOX2 and PHYHIP, showed no significant protein expression in tumor tissues; the THRB showed “low intensity”, RBBP8 and ST18 showed “medium intensity”, and, interestingly, the TCF12 showed “high intensity”." (PMID 40869909, 2025).
ST18 also shares sentences with these, for which no sentence is quoted: cancer (6 papers); Anxiety (1); atherosclerosis (1); autoimmune disease (1); Autoimmunity (1); bladder cancer (1); colorectal tumors (1); cortical atrophy (1); depression (1); Diabetes (1); Down syndrome (1); esophageal cancer (1); hepatocellular carcinoma (1); leukemia (1); ovarian carcinoma (1); primary angle-closure glaucoma (1); small cell lung carcinoma (1).